CDKN3 (cyclin dependent kinase inhibitor 3)
Diseases named in the same sentence as CDKN3 in open-access papers (continued):
Sharing a sentence is not in itself a finding about the gene and the disease.
renal cell carcinoma (10 papers, 2012 to 2024). "Aolin Li and colleagues demonstrated that ZNF677 represses the malignant evolution of renal cell carcinoma through the reduction of CDKN3 expression." (PMID 38953023, 2024). "It has been proven that ZNF677 inhibits the progression of renal cell carcinoma through the transcription of N6 methyladenosine and CDKN3." (PMID 38720365, 2024). "ZNF677 plays a tumor suppressor role in renal cell carcinoma (RCC) through transcriptionally repressing its downstream target CDKN3." (PMID 37264402, 2023). "Moreover, additional investigations have validated that increased CDKN3 expression promotes proliferation and metastasis of renal cell carcinoma." (PMID 38720365, 2024). "Furthermore, the circular RNA circSDHC binds to miR-127–3p competitively, thereby diminishing CDKN3 expression in renal cell carcinoma and curbing its malignant advancement." (PMID 38953023, 2024). "The circSDHC / miR-127-3p / CDKN3 / E2F1 axis promotes renal cell carcinoma progression." (PMID 34716323, 2021). "CircRNA also plays an important role in the development of renal cell carcinoma (RCC) by regulating CDKN3/E2F1 in combination with miR-127-3p." (PMID 36138829, 2022). "In addition, elevated levels of CDKN3 occur in renal cell carcinoma (RCC), and enforced CDKN3 expression significantly enhances cell proliferation and xenograft tumor growth in renal cancer cells, suggesting an oncogenic function of CDKN3." (PMID 25360622, 2014).
colon carcinoma (8 papers, 2006 to 2024). "TCF3 upregulation is caused by promoter hypomethylation during development, colon cancer progression, and the transcriptional upregulation of multiple cyclin-dependent kinase inhibitors like CDKN1A, p15INK4B, and p16INK4B, and probably CDKN3 in colon cancer." (PMID 39228892, 2024). "This study revealed that remimazolam promoted the cell-cycle progression and proliferation of HCT8 colon cancer cells by upregulating CDK1, PTTG1, CDC25C, CDK4, PLK1, PCNA, Ki67, RNASEH2B, FEN1, Cyclin D1,CD44 CDK2, CDKN3, CDC45, IQGAP3, and CDK6." (PMID 38725628, 2024).
esophageal cancer (8 papers, 2021 to 2025). A primary or metastatic malignant neoplasm involving the esophagus. "KIF4A-based multi-gene signatures, such as KIF4A + RAD51AP1 + CDKN3 in oesophageal cancer, are poised to enter clinical practice as routine tools for molecular diagnostics and prognostic predictions, enabling more precise patient stratification." (PMID 41361459, 2025). "CDKN3 regulates the cell cycle and chemo-resistance in esophageal cancer, which promotes cancer progression." (PMID 36499614, 2022). "In esophageal cancer, CDKN3 affects the progress of cancer by promoting cell cycle and chemotherapy." (PMID 36147496, 2022). "In esophageal cancer, CDKN3 influences cancer progression by promoting the cell cycle and chemo-resistance." (PMID 33468140, 2021).
glioblastoma (7 papers, 2013 to 2026). The most malignant astrocytic tumor (WHO grade IV). "However, overexpression of CDKN3 has been associated with the inhibition of cell proliferation in glioblastoma and leukemic cell lines." (PMID 26372210, 2015). "CDKN3 has been found to be upregulated in breast, prostate, ovary, lung, renal, glioblastoma, liver, neuroendocrine, and oral cancers." (PMID 26372210, 2015). "However, there is controversy over the role of CDKN3 in different tumours; some studies suggest that CDKN3 is a tumour suppressor gene, since CDKN3 inhibits cell proliferation in glioblastoma, chronic myeloid leukaemia, and neuroblastoma." (PMID 32000807, 2020). "For example, in a study conducted in Glioblastoma multiforme (GBM), it was shown that CDKN3 protein was downregulated in GBM compared to normal tissue and CDKN3 played a role in controlling mitosis." (PMID 38356706, 2024).
liver cancer (7 papers, 2020 to 2025). An epithelial or non-epithelial malignant neoplasm that arises from the liver. "Moreover, because CDKN3 is intimately linked to the occurrence, development and prognosis of liver cancer, it may be of value for the early diagnosis and treatment of tumours." (PMID 32000807, 2020). "It was found that, compared with the adjacent samples, the mRNA expression of the CDKN3 gene was significantly upregulated in 63.9% (23/36) of liver cancer tissues." (PMID 40302936, 2025). "Although previous studies have explored the molecular mechanism by which CDKN3 regulates the conversion from liver cirrhosis to liver cancer, only one database study explored differences in CDKN3 between HCC and liver cirrhosis." (PMID 32000807, 2020). "In order to explore the mechanism by which CDKN3 influences the occurrence and development of liver cancer, we used bioinformatics tools to screen genes related to changes in CDKN3, and SPC25, CDK1 and CCNB2 were identified." (PMID 32000807, 2020). "By compared liver cancer, cirrhosis, and normal tissues, CDKN3 was found to be significantly increased in HCC tissues, but the difference was not significant between cirrhosis and normal tissues." (PMID 32000807, 2020). "Therefore, the expression levels of AURKA, BIRC5, CCNB1, CDK1, CDKN3 and TYMS served as diagnostic markers for liver cancer patients." (PMID 37393234, 2023). "Moreover, silencing the expression of CDKN3 could induce G0/G1 phase arrest in liver cancer cells, indicating that CDKN3 promotes the proliferation of liver cancer cells by affecting the cell cycle distribution." (PMID 40302936, 2025). "Q-PCR and Western blotting were used to detect the expression of CDKN3 in LIHC and its adjacent tissues as well as human liver cancer cell lines." (PMID 40302936, 2025).
neuroblastoma (6 papers, 2020 to 2025). Neuroblastoma (NB) is the most common solid, extracranial childhood tumor. "Together with the oncogenic function of CDKN3 that we observed as above, these results suggest that CDKN3 may represent one of the key signaling pathways underlying the congenic function of N-Myc in neuroblastoma." (PMID 38356706, 2024). "We further examined the effect of N-Myc on CDKN3 mRNA levels in additional neuroblastoma cell lines." (PMID 38356706, 2024). "The novelty of our study lies in three aspects: 1) We are the first to characterize the function of CDKN3 in modulating neuroblastoma cell differentiation." (PMID 38356706, 2024). "To preliminarily evaluate the potential clinical relevance of our laboratory findings in neuroblastoma patients, we investigated the correlation of neuroblastoma tumor CDKN3 mRNA expression with patient survival." (PMID 38356706, 2024). "Our investigation based on public neuroblastoma datasets preliminarily supports the correlation of high tumor CDKN3 mRNA levels with poor patient survival in most of the patient subgroups." (PMID 38356706, 2024). "The results suggest that CDKN3 plays an important role in the cell signaling pathways that determine neuroblastoma cell fate, with depletion of CDKN3 expression promoting cell differentiation." (PMID 38356706, 2024). "We then demonstrated that CDKN3 knockdown increased expression of neuroblastoma molecular differentiation markers, neuron specific enolase (NSE), βIII-tubulin and growth associated protein 43 (GAP43)." (PMID 38356706, 2024). "More importantly, we found that MYCN mRNA levels in neuroblastoma tumor specimens are positively and significantly correlated with CDKN3 mRNA levels in all the three independent patient datasets." (PMID 38356706, 2024). "Future prospective studies with larger sample sizes are certainly needed to further validate the clinical significance of CDKN3 overexpression in neuroblastoma." (PMID 38356706, 2024). "To examine the clinical relevance of elevated CDKN3 expression in neuroblastoma, we investigated the correlation of CDKN3 mRNA levels in neuroblastoma tumor specimens with patient survival based on three public patient datasets in the R2 Genomics platform." (PMID 38356706, 2024). "Our results presented in this study for the first time demonstrate that CDKN3 plays an important role in regulating neuroblastoma cell differentiation." (PMID 38356706, 2024). "Through a HCS screening, we identified CDKN3 as a strong regulator of neuroblastoma cell differentiation." (PMID 38356706, 2024). "Since the main goal of the current study is to experimentally characterize the function of CDKN3 in cultured neuroblastoma cells, we only preliminarily investigated the potential clinical relevance of our laboratory findings." (PMID 38356706, 2024). "In summary, we for the first time discovered the function of CDKN3 in regulating neuroblastoma cell differentiation and characterized the transcriptional regulation of CDKN3 expression by N-Myc in neuroblastoma cells." (PMID 38356706, 2024). "More importantly, we observed a correlation of high tumor CDKN3 mRNA levels with poor patient survival in the investigation of public neuroblastoma patient datasets." (PMID 38356706, 2024). "However, no published study has been conducted to systematically characterize the role of CDKN3 in regulating cell differentiation in neuroblastoma." (PMID 38356706, 2024). "We identified CDKN3 as potent modulator of neuroblastoma cell differentiation." (PMID 38356706, 2024). "Our findings support that CDKN3 plays a role in modulating neuroblastoma cell differentiation and that overexpression of CDKN3 may contribute to neuroblastoma progression." (PMID 38356706, 2024).
neuroblastoma (continued). "Given the statistical significance observed in the other two datasets for stage 1 patients, our results support the correlation of high CDKN3 level with low patient survival in stage 1 patients, although this will need to be further validated in future studies in additional neuroblastoma patients." (PMID 38356706, 2024). "The model containing CNR1, PRKACB, CDKN3, and PCLAF can serve as a new prognostic biomarker for predicting the prognosis of patients with neuroblastoma." (PMID 40302936, 2025). "CNR1, PRKACB, CDKN3, and PCLAF were found to significantly affect the overall survival and event-free survival of neuroblastoma patients and were positively correlated with the INSS advanced stages." (PMID 40302936, 2025). "We further showed that CDKN3 knockdown reduced expression of cell proliferation markers Ki67 and proliferating cell nuclear antigen (PCNA), and reduced colony formation of neuroblastoma cells." (PMID 38356706, 2024). "We discovered that knocking down expression of cyclin dependent kinase inhibitor 3 (CDKN3) showed the most potent effect in inducing neurite outgrowth, the morphological cell differentiation marker of neuroblastoma cells." (PMID 38356706, 2024). "Altogether, these results support the clinical significance of the interaction network formed by CDKN3, CDC6 and CDK4 in neuroblastoma." (PMID 38356706, 2024). "Finally, both the mRNA and protein expression verification assays demonstrated that the CDKN3 and PCLAF were upregulated, while the PRKACB was downregulated in advanced-stage neuroblastoma tissue samples." (PMID 40302936, 2025). "Four prognostic genes (CNR1, PRKACB, CDKN3, and PCLAF) were identified, and a prognostic model based on these genes was developed that provides novel insights into the prognostic evaluation of neuroblastoma." (PMID 40302936, 2025). "In addition, since MYCN is a well-known oncogene that plays a key role in maintaining the undifferentiated status of neuroblastoma cells 38, we also tested the effect of MYCN knockdown on CDKN3 expression." (PMID 38356706, 2024). "However, the role of CDKN3 in modulating neuroblastoma cell differentiation has not been investigated previously." (PMID 38356706, 2024). "However, the role of CDKN3 in regulating neuroblastoma cell differentiation has not been reported previously." (PMID 38356706, 2024).
clear cell renal cell carcinoma (5 papers, 2020 to 2024). "As a continuation of the ongoing efforts to elucidate the molecular characteristics of clear cell renal cell carcinoma (ccRCC); we present a comprehensive bioinformatics study targeting the prognostic and mechanistic role of cyclin-dependent kinase inhibitor 3 (CDKN3) in ccRCC." (PMID 37682177, 2023). "Besides, high CDKN3 mRNA levels commonly occurred and were associated with poor OS in a variety of human cancer cells, such as LGG, renal clear cell carcinoma, and prostate adenocarcinoma." (PMID 36419652, 2022). "In addition, CDKN3 expression followed the same trend in renal neoplasms including chromophobe (KICH), papillary, and clear cell renal cell carcinomas (KIRC)." (PMID 37682177, 2023).
esophageal squamous cell carcinoma (5 papers, 2021 to 2024). Esophageal squamous cell carcinoma (ESCC) is a type of esophageal carcinoma (EC) that can affect any part of the esophagus, but is usually located in the upper or middle third. "An immunohistochemical study for ESCC identified abnormal CDKN3 protein expression in esophageal squamous-cell cancer (ESCC) patients and confirmed its association with ESCC progression." (PMID 37489460, 2023). "In addition, the study of Cyclin-dependent kinase inhibitor-3 (CDKN3) revealed that overexpression of CDKN3 promoted cell proliferation, migration, and invasion in esophageal squamous cell carcinoma." (PMID 34795689, 2021).
nasopharyngeal carcinoma (5 papers, 2021 to 2024). A carcinoma arising from the nasopharyngeal epithelium. "Current evidence suggests that CDKN3 is positively associated with TNM stages but negatively with disease-specific survival of nasopharyngeal carcinoma." (PMID 36471446, 2022). "In addition, CDKN3 has been shown to be an independent prognostic factor that contributes to the progression of nasopharyngeal carcinoma to advanced stage." (PMID 38720365, 2024).
leukemia (4 papers, 2010 to 2020). A malignant (clonal) hematologic disorder, involving hematopoietic stem cells and characterized by the presence of primitive or atypical myeloid or lymphoid cells in the bone marrow and the blood. "Our experiments presented above demonstrated that the phosphatase activity of CDKN3 is essential for its pro-apoptotic activity in the CML leukemia cells." (PMID 25360622, 2014). "Overexpression of CDKN3 delayed G1/S transition, sensitized imatinib-induced apoptosis in K562 leukemic cells, and inhibited the growth of xenografted leukemias in nude mice." (PMID 25360622, 2014). "Our results highlight the importance of CDKN3 in Bcr-Abl-mediated leukemogenesis, and provide new insights into diagnostics and therapeutics of the leukemia." (PMID 25360622, 2014). "In contrast, depletion of CDKN3 expression conferred resistance to imatinib-induced apoptosis in the leukemic cells and accelerated the growth of xenograph leukemia in mice." (PMID 25360622, 2014). "Since overexpression of CDKN3 inhibited the growth of leukemia in vivo, we hypothesized that decreased CDKN3 expression may promote the growth of leukemic tumors." (PMID 25360622, 2014). "Despite the importance of CDKN3 in tumorigenesis, how CDKN3 plays a role in Bcr-Abl-induced leukemia and the mechanism by which CDKN3 functions to impact Bcr-Abl-mediated cellular transformation are largely unknown." (PMID 25360622, 2014). "In addition, future work will also explore the proposed role of inactivation of the CDKN3 tumor suppressor pathway in human leukemia." (PMID 25360622, 2014). "However, the functional relevance of CDKN3 in Bcr-Abl-mediated leukemias remains elusive." (PMID 25360622, 2014).
liver cirrhosis (4 papers, 2017 to 2021). "The analysis of the nine genes, namely A2m, Akr7a3, Aqp7, Ca3, Cdc2a, Cdkn3, Cyp2c11, Ntf3, and Sds, revealed the association between NGHCs and chronic inflammatory liver conditions, including liver cirrhosis and fibrosis." (PMID 32560183, 2020). "By integrating multiple microarray gene expression profiles, three key genes (LCAT, CYP2C9, and CDKN3) were identified that appear to be important for the conversion of liver cirrhosis into HCC." (PMID 32000807, 2020). "CDKN3 may affect the transformation of liver cirrhosis into HCC, and represents a new candidate molecular marker of the occurrence and progression of HCC." (PMID 32000807, 2020). "Notably, through literature reviews, we found that CLDN10, CDKN3, CRHBP and NEK2 were reported to be associated with HCC, and SPINK1 was associated with liver cirrhosis." (PMID 28036264, 2017).
non-small cell lung carcinoma (4 papers, 2016 to 2024). A group of at least three distinct histological types of lung cancer, including non-small cell squamous cell carcinoma, adenocarcinoma, and large cell carcinoma. "A study showed that miR-181d-5p directly repressed CDKN3 protein expression by binding to a target site in the 3'UTR of CDKN3 mRNA in non-small cell lung cancer 52, and this regulation was later confirmed by another research group 53." (PMID 38356706, 2024). "There is a theoretical possibility that hsa-miR-181d-5p may regulate CDKN3 expression through the AKT signaling pathway, thereby potentially influencing the progression of non-small cell lung carcinoma." (PMID 37682177, 2023).
renal carcinoma (4 papers, 2014 to 2024). A carcinoma arising from the epithelium of the renal parenchyma or the renal pelvis. "Overexpression of CDKN3 enhances also cell proliferation in renal cancer cells." (PMID 26859141, 2016). "Intriguingly, despite the expressions of BID, CDKN3, and PLK1 being consistently higher in the renal carcinoma cell lines than in the normal renal cells across both the primary and tenth passages, shifts in the gene expression levels among the carcinoma lines were noted." (PMID 38953023, 2024).
chronic myelogenous leukemia (3 papers, 2014 to 2020). "However, the role of CDKN3 in Bcr-Abl-mediated chronic myelogenous leukemia (CML) remains unknown." (PMID 25360622, 2014).
COVID-19 (3 papers, 2023). A disease caused by infection with severe acute respiratory syndrome coronavirus 2. "The CDKN3 gene could be used as a potential marker to identify severe COVID-19 patients." (PMID 37489460, 2023). "In our study, seven genes (BUB1, PRC1, KIFC1, RRM2, CDKN3, CCNB2, and MCM6) were involved in the interaction between COVID-19 and silicosis." (PMID 37278873, 2023). "Then, five important IADEGs (AXL, MKI67, CDKN3, BCL2 and PTGS2) for severe COVID-19 were screened by random forest analysis." (PMID 37113134, 2023). "On the contrary, CDKN3 and MKI67 were clustered as another group with low expression in the normal sample and high expression in the COVID-19 sample." (PMID 37113134, 2023). "Finally, submodule analysis showed that PRC1, KIFC1, BUB1, MCM6, CCNB2, CDKN3, and RRM2, which were hub-shared genes of silicosis and COVID-19, possessed the highest mCODE scores." (PMID 37278873, 2023). "Furthermore, AXL, MKI67, CDKN3, BCL2 and PTGS2 as a marker combination could be used as potential markers to identify severe COVID-19 patients." (PMID 37113134, 2023). "Therefore, AXL, MKI67, CDKN3, BCL2 and PTGS2 might be key markers for occurrence and development of severe COVID-19." (PMID 37113134, 2023).
oral cancer (3 papers, 2015 to 2024). "Based on the gene specificity of selected genes modulated by anethole in Ca9-22 oral cancer cells, we found that two out of the 13 analyzed genes (CDKN3 and CUL2) were involved in the G1 phase & G1/S transition." (PMID 39689117, 2024).
pancreatic ductal adenocarcinoma (3 papers, 2020 to 2023). An infiltrating adenocarcinoma that arises from the epithelial cells of the pancreas. "As an example, YY1 restrains pancreatic ductal adenocarcinoma cell proliferation and migration through transcriptionally activating CDKN3 expression." (PMID 32943988, 2020).
brain tumors (2 papers, 2015 to 2023). "In addition, CDKN3 has been proposed to be a tumor suppressor gene of brain tumors and of mitosis control." (PMID 26372210, 2015).